RPP25L (ribonuclease P/MRP subunit p25 like)
Description:
May be a component of ribonuclease P or MRP.
Synonyms: C9orf23; bA296L22.5; MGC29635
Tractability: PROTAC: ubiquitination databases record sites on it; its protein half-life has been measured.
Gene: Protein-coding gene on chromosome 9 (34,610,486 to 34,612,605, reverse strand). Ensembl gene ENSG00000164967.
Subcellular location: Nucleus
Subcellular location (Human Protein Atlas): Nucleoplasm; Cytosol; Nucleoli
Gene Ontology:
Molecular function: protein binding; RNA binding; nucleic acid binding
Biological process: tRNA 5'-leader removal
Cellular component: ribonuclease MRP complex; nucleus
Genetic constraint (gnomAD): Loss-of-function variants: 5 observed, 10.51 expected, observed/expected ratio (o/e) 0.48, 90% interval 0.25 to 1. The upper end of that interval is the gene's LOEUF score, 1, which puts it in group 4 of 6, group 1 being the genes least tolerant of losing a copy. Missense variants: 192 observed, 227.41 expected, observed/expected ratio (o/e) 0.84, 90% interval 0.75 to 0.95. Synonymous variants: 96 observed, 91.27 expected, observed/expected ratio (o/e) 1.05, 90% interval 0.89 to 1.25.
Homologues: Orthologues: chimpanzee RPP25L (100% identical), macaque RPP25L (100% identical), pig RPP25L (98% identical), rabbit RPP25L (96% identical), rat Rpp25l (95% identical), guinea pig RPP25L (94% identical), mouse Rpp25l (94% identical), tropical clawed frog rpp25l (56% identical), zebrafish rpp25l (50% identical), Drosophila melanogaster Rpp25 (33% identical), Caenorhabditis elegans ZK632.14 (25% identical). Paralogues in human: RPP25 (41% identical).
Diseases named in the same sentence as RPP25L in open-access papers:
RPP25L is named in the same sentence as 1 disease in open-access papers, as found by Europe PMC text mining. Sharing a sentence is not in itself a finding about the gene and the disease. The quoted sentences say what the papers report.
glioma (1 paper, 2023). A benign or malignant brain and spinal cord tumor that arises from glial cells (astrocytes, oligodendrocytes, ependymal cells). "In glioma cells, this study identified RPP25L as a novel Supertarget." (PMID 37297004, 2023).